EZH2 (enhancer of zeste 2 polycomb repressive complex 2 subunit)
Diseases named in the same sentence as EZH2 in open-access papers (continued):
Sharing a sentence is not in itself a finding about the gene and the disease.
Anxiety (continued). "The authors found that the microRNA, miR-101a-3p and its target Ezh2 in the amygdala, are involved in rat anxiety-like behaviour." (PMID 35938156, 2022). "The miR-101a-3p and its target, enhancer of zeste homolog 2 (Ezh2) in the amygdala, contribute to anxiety-like behavior." (PMID 32218741, 2020). "Here we observed a higher expression level of EZH2 in the forebrain of miR-137 cKO mice that displayed anxiety-like behavior." (PMID 31736707, 2019). "We tested whether AIE would produce anxiety-like behaviors in female rats similar to those previously observed in male rats as well as whether EZH2 knockdown in the CeA would prevent AIE-induced anxiety-like behaviors in adulthood." (PMID 38670959, 2024). "In adulthood, EZH2 is essential in neurogenesis, memory, and anxiety." (PMID 38670959, 2024). "Furthermore, bioinformatics analysis and experimental data showed that EZH2 is a target gene of miR-124-3p and that increased EZH2 expression is involved in visceral hypersensitivity and anxiety in IBS-like rats by regulating synaptic plasticity." (PMID 36467610, 2022). "Furthermore, bioinformatic analysis and experimental data showed that EZH2 is a circKcnk9/miR-124-3p target gene, and increased EZH2 expression was involved in visceral hypersensitivity and anxiety in IBS-like rats by enhancing hippocampal synaptic plasticity." (PMID 36467610, 2022). "Consistently, EZH2 expression was also increased in subjects harassed from anxiety." (PMID 35172677, 2022). "Interestingly, overexpress of miR-101a-3p in the amygdala of high-novelty-responding (HR) rats increased their anxiety-like behavior at least partially mediated via downregulation of EZH2." (PMID 31736707, 2019). "Elevated EZH2 expression has been shown in individuals with severe anxiety." (PMID 31736707, 2019). "Given that EZH2 is a well-characterized transcription repressor that is highly expressed in NSPCs but decreased upon neuronal differentiation, an important question that remains unanswered is how the upregulation of EZH2 contribute to anxiety." (PMID 31736707, 2019). "However, neuronal-specific EZH2 knockout exerted only minimal effects on these gut microbiota—induced anxiety-like behaviors: it partially reduced the number of buried marbles in the marble burying test but failed to significantly improve performance in the open field or elevated plus maze tests." (PMID 41041075, 2025). "Here, we identified EZH2 as an epigenetic target that regulates histone acetylation and methylation marks at the Arc SARE site and controls AIE-induced anxiety-like behaviors in adulthood in both sexes." (PMID 38670959, 2024). "However, there is not enough literature that evaluates the effect of adolescent alcohol exposure on adult anxiety-related behaviors in both male and female preclinical models or whether EZH2 regulates this phenotype and Arc expression via epigenetic modifications of the Arc SARE site in both sexes." (PMID 38670959, 2024). "Future studies are needed to establish the link between EZH2 mediated epigenetic mechanisms and synaptic regulation in PKC-δ positive GABAergic neurons in CeA to AIE-induced anxiety-like behaviors in both sexes." (PMID 38670959, 2024). "Our data suggest the possibility that higher EZH2 levels may decrease the inhibitory response of PKC-δ positive GABAergic neurons in the CeA and contribute to regulation of anxiety phenotype after AIE in adulthood." (PMID 38670959, 2024).
invasive breast carcinoma (11 papers, 2016 to 2025). A carcinoma that infiltrates the breast parenchyma. "EZH2 overexpression is reported in up to 55% of invasive breast cancer and is strongly associated with ER-/PR- status, high histological grade, and TNBC phenotype." (PMID 41516003, 2025). "To better elucidate the relevance of EZH2 in breast cancer subtypes, we evaluated EZH2 expression in 226 invasive breast carcinomas with four distinct immunophenotypes and in association with clinicopathological features." (PMID 27113214, 2016). "So, in this study, EZH2 expression in 226 invasive breast carcinomas was assessed by IHC, and the association with clinicopathologic features was analyzed in Chinese cohort." (PMID 27113214, 2016). "Increased expression of EZH2 associates with decreased nuclear expression of phospho-BRCA1 (Ser1423) and upregulation of phospho-Akt-1 (Ser473) in ~ 40% of invasive breast carcinomas." (PMID 33330580, 2020). "It has been found that the downregulation of EZH2 decreases invasive breast cancer and requires BRCA1." (PMID 31213036, 2019). "Overexpression of EZH2 is able to activate the PI3K/AKT pathway, by which BRCA1 (a tumor suppressor) were exported from nuclei, and aneuploidy and mitotic deficiency were elicited, leading to invasive breast cancer." (PMID 34257531, 2021). "Moreover, it was reported that EzH2 downregulation could reduce growth of invasive breast carcinoma, tumor angiogenesis and in vitro cell migration/invasion of CRC cell lines." (PMID 29285251, 2017). "We investigated the mechanisms involved in the regulation of ECM remodeling by EZH2 by performing starBase v2.0 analysis to evaluate the correlation between EZH2 and LOX family proteins, which play a critical role in the formation and repair of the ECM in invasive breast carcinoma." (PMID 32754259, 2020).
kidney cancer (11 papers, 2013 to 2025). Primary or metastatic malignant neoplasm involving the kidney. "EZH2 is often overexpressed in many cancer types, including prostate, breast, and kidney cancer, and EZH2 overexpression is associated with poor patient outcomes (13, –15)." (PMID 33593912, 2021). "Using immunohistochemistry, EZH2 protein was detected in 44% of 110, 78% of 165, 84% of 119, 89% of 520, 100% of 257, 100% of 185, and 100% of 50 kidney cancers." (PMID 32303902, 2021). "For example, EZH2 a specific histone methyl transferase is a driver of sunitinib resistance in kidney cancers." (PMID 32775327, 2020). "In this review, we highlight the transcriptional function of EZH2 in cancer and the current insights into the role of EZH2 in prostate, bladder and kidney cancer." (PMID 28410242, 2017). "Enhancer of zeste homolog 2 (EZH2) is of potential interest in kidney cancer." (PMID 32303902, 2021). "In this study EZH2 immunostaining was seen in 75.2% of kidney cancers." (PMID 32303902, 2021). "Based on these observations, one might speculate that lymphocytic infiltration might cause a particular strong EZH2 overexpression in RCC and the resulting immune evasion causes the poor patient outcome in kidney cancers with high CD8+ cell density." (PMID 32303902, 2021). "It showed that mRNA levels of EZH2 were more than fourfold higher in kidney cancer cell lines." (PMID 30755832, 2019). "Except for EZH2, few of them were frequently identified and studied in kidney cancer." (PMID 30755832, 2019).
overgrowth syndrome (11 papers, 2016 to 2024). A group of syndromes caused by genetic birth defects that may lead to the development of malignancies. "Consistent with this idea, mutations in the DNA methyltransferase gene DNMT3A, SETD2 and EZH2 have also been shown to cause overgrowth syndromes." (PMID 27688808, 2016). "EZH2, EED, and SUZ12 are components of the polycomb repressive complex 2 (PRC2), and this likely explains why genetic changes in these genes cause similar overgrowth syndromes." (PMID 36927955, 2023). "This was consistent with these diseases being distinct, although extensive overlap of clinical signs between SETD2-associated phenotypes and other overgrowth syndromes related to NSD1, EZH2 or DNMT3A in Sotos, Weaver and Tatton-Brown-Rahman syndromes, respectively, has been reported." (PMID 33916664, 2021).
retinoblastoma (11 papers, 2013 to 2024). A malignant tumor that originates in the nuclear layer of the retina. "Ectopic expression of miR-101 significantly reduced cell growth and proliferation in retinoblastoma through directly targeting EZH2, which was associated with increased G1 phase arrest and cell apoptosis." (PMID 26633386, 2015). "One, EZH2 may serve as a diagnostic biomarker to detect invasive IM tumor cells in the ciliary body, retina, iris, and possibly optic nerve or extraocular tissues, similar to retinoblastoma." (PMID 27842164, 2016). "EZH2 inhibitor has been reported to be efficient efficacy in RB1-mutational Y79 and Weri retinoblastoma cells." (PMID 36175480, 2022). "A recent study reported that miR-101-3p prevented retinoblastoma cell proliferation by targeting EZH2 and HDAC9." (PMID 34307682, 2021). "Within the recurrent focal gains or losses in the RbTKO retinoblastoma model, we found 12 in cancer genes, including Lmo1 in 5/6 samples; Ndrg1, Brd4, Fbxo11, and Rbm15 in 4/6 samples; Mdm4, Msi2, and Ezh2 in 3/6 samples." (PMID 23765217, 2013). "The miR-101 functions as a tumor suppressor in human retinoblastoma cells by targeting EZH2." (PMID 26633386, 2015). "Additionally, upregulation of miR-101-3p has been reported to suppress EZH2 and HDAC9 expression, thereby inhibiting cell cycle progression in retinoblastoma cells." (PMID 37887350, 2023). "For instance, numerous studies showed that the presence of many dysregulation CRs (e.g., UHRF1, DNMT1, EZH2, BMI1 and HELLS) might lead to an abnormal epigenetic landscape in retinoblastoma (RB), which might be associated with tumorigenesis and malignant progression." (PMID 36318256, 2023). "In our recent report of EZH2 expression in retinoblastoma (RB), we found that while EZH2 appears to be a specific marker for RB, it did not mark all RB cells." (PMID 27842164, 2016). "Similar to retinoblastoma, moderately to poorly differentiated (primitive appearing) IM tumor cells strongly expressed EZH2; expression was weaker or absent in areas of well-formed neuroepithelial units." (PMID 27842164, 2016). "Indeed, we found that small molecule EZH2 inhibitors related to those currently in early phase clinical trials, uniquely target retinoblastoma tumor cells but spare nontumor RPE cells in vitro." (PMID 27842164, 2016).
serous ovarian cancer (11 papers, 2004 to 2025). "A recent report using 17 primary serous ovarian cancer patients and in vitro models showed that EZH2 loss drives resistance to carboplatin and paclitaxel in serous ovarian cancers that express Ataxia Telangiectasia Mutated (ATM)." (PMID 36230683, 2022). "CRABP2 enhances the methylation of TRIM16 by elevating EZH2 expression, subsequently expediting the epithelial-mesenchymal transition in serous ovarian cancer cells." (PMID 39991584, 2025). "miRNA‐506‐3p targets EZH2 and negatively modulates the expression of β‐catenin in serous ovarian cancer." (PMID 34890108, 2022). "The aim of this study was to comprehensively assess the prognostic value of EZH2 across the morphologic and molecular spectra of high-grade serous ovarian carcinoma (HGSOC) by utilizing both immunohistochemistry (IHC) and proteogenomic technologies." (PMID 34140011, 2021). "We found that, within the stage III serous ovarian adenocarcinomas, a number of predictive genes including EZH2, PTTN and Lamin-B are overexpressed in primary, at least as highly as in omental metastases." (PMID 14760385, 2004). "Moreover, CRABP2 had been observed in serous ovarian cancer cells to enhance TRIM16 methylation through upregulation of EZH2, resulting in enhanced EMT effect." (PMID 38186580, 2023). "CDK2-mediated phosphorylation of EZH2 at T416 activates EZH2 to silence target genes—ERα gene (ESR1), leading to in high-grade serous ovarian carcinoma (HGSOC) and TNBC." (PMID 37803297, 2023). "We cross-referenced the list of 218 direct EZH2/H3K27Me3 target genes with 528 TCGA high-grade serous ovarian carcinomas gene expression profiles and identified genes that negatively correlated with CARM1 expression in these cases." (PMID 29434212, 2018).
soft tissue sarcoma (11 papers, 2011 to 2025). A malignant neoplasm arising from muscle tissue, adipose tissue, blood vessels, fibrous tissue, or other supportive tissues excluding the bones. "Our study suggests that unfavourable outcome and tumor progression of paediatric soft tissue sarcoma is linked to abnormal over-expression of EZH2 and malignancy grade is its effect." (PMID 27471434, 2016). "In this study, we report, for the first time, that the microRNA miR-101 is down-regulated in the most recurrent variant of pediatric soft tissue sarcoma, i.e., the embryonal rhabdomyosarcoma (eRMS), showing an inverse pattern of expression with the histone methyltransferase EZH2." (PMID 26251675, 2015). "This is a first-in-class, oral, small-molecule selective inhibitor of EZH2 and was also the first epigenetic regulating agent approved for soft tissue sarcoma." (PMID 38310286, 2024). "In conclusion, our data provide evidence that EZH2 abnormal over-expression is involved in sustaining proliferation and inhibiting myogenic differentiation of paediatric soft tissue sarcomas." (PMID 27471434, 2016). "EZH2 deregulated expression/function in soft tissue sarcomas has been recently reported." (PMID 21609503, 2011). "In this review, an overview of the recently reported functions of EZH2 in soft tissue sarcomas is given and the hypothesis that its expression might be involved in soft tissue sarcomagenesis is discussed." (PMID 21609503, 2011). "Some studies exist also on adult sarcomas such as synovial sarcomas in which it was found that high EZH2 expression is predictive of developing distant metastases even in the better-differentiated subtypes.On the other hand, poor data are available on childhood soft tissue sarcomas." (PMID 27471434, 2016). "In the present manuscript, we have studied the expression of the polycomb complex proteins EZH2, SUZ12 and EED in paediatric soft tissue sarcomas correlating the expression with the clinical outcome of the patients." (PMID 27471434, 2016). "Further, whereas Ki-67 as a well-established prognostic marker in soft tissue sarcomas proved to be a superior predictor of overall survival, high EZH2 status – but not high H3K27me3 or high Ki-67 – was found to be predictive of distant metastasis in the MPSS+BPSS group." (PMID 23110793, 2012).
tongue squamous cell carcinoma (11 papers, 2016 to 2025). A squamous cell carcinoma that arises from the tongue. "In tongue squamous cell carcinoma, EZH2 inhibits erastin-induced ferroptosis through the miR-125b-5p/SLC7A11 pathway rather than the H3K27me3 pathway." (PMID 41372608, 2025). "In tongue squamous cell carcinoma, EZH2 repression of miR-125b-5p has been reported, leading to enhanced SLC7A11 expression, thereby averting erastin-induced ferroptosis." (PMID 39516467, 2024). "Actually, a previous study also has demonstrated that BMAL1 transcriptionally down-regulates its downstream target TERT in an EZH2-dependent manner in tongue squamous cell carcinoma cells." (PMID 36439870, 2022). "For instance, lncRNA H19 contributes to progression of tongue squamous cell carcinoma through interaction with EZH2." (PMID 33292221, 2020). "BMAL1 also increases sensitivity to paclitaxel in tongue squamous cell carcinoma by recruiting enhancer of zeste homolog 2 (EZH2) repressors to the telomerase reverse transcriptase (TERT) promoter to prohibit TERT transcription." (PMID 32231148, 2020). "Another study, by Wang and colleagues, found that EZH2-mediated E-cadherin repression promoted metastasis in tongue squamous cell carcinoma." (PMID 26848980, 2016). "SLC7A11, mediated by EZH2, regulated the ferroptosis in tongue squamous cell carcinoma." (PMID 35997855, 2023).
diffuse midline glioma (10 papers, 2022 to 2025). A diffuse glioma that arises from the midline structures of the central nervous system. "For instance, inhibition of microglial enhancer of zeste homolog 2 (EZH2) demonstrates antitumor effects in pediatric diffuse midline gliomas, highlighting microglia as a promising therapeutic target." (PMID 41272822, 2025). "Recently, Keane and colleagues were able to show that silencing of EZH2 in BV2 microglia results in significantly increased phagocytosis of diffuse midline glioma cells." (PMID 36555253, 2022). "Furthermore, diffuse midline glioma with high EZH2 expression carried a worse prognosis than diffuse glioma and diffuse midline glioma with low EZH2 expression." (PMID 39636550, 2025). "In addition, combined analysis of H3K27me3 and EZH2 was beneficial in the prognostic prediction of spinal diffuse midline glioma." (PMID 39636550, 2025). "Interestingly, inhibiting EZH2 has also shown promise in the lab as a therapeutic for diffuse midline glioma, even though H3K27me3 levels are already significantly reduced." (PMID 36359771, 2022). "H3K27me3 is used as a diagnostic marker for diffuse midline glioma and as a surrogate marker to distinguish posterior fossa ependymoma A and B. However, the clinical significance of the EZH2–H3K27me3 axis in astrocytoma, IDH-mutant has not been reported, prompting this investigation." (PMID 39636550, 2025). "In other words, EZH2 inhibition in microglia rather than tumour cells has antitumoral effects in diffuse midline glioma." (PMID 36555253, 2022).
inflammatory bowel disease (10 papers, 2018 to 2025). A spectrum of small and large bowel inflammatory diseases of unknown etiology. "Notwithstanding, the functions of EZH2 have been reported in a much wider range of disorders including inflammatory bowel disease, or even the pathogenesis of subarachnoid hemorrhage and ischemic stroke." (PMID 40723311, 2025). "Bamidele and colleagues looked at the interaction of EZH2 and FOXP3 in inflammatory bowel disease and found that a mutation in FOXP3 disrupted EZH2 recruitment and its co-repressive function." (PMID 33800594, 2021). "Mice that specifically lack EZH2 expression in Treg develop spontaneous inflammatory bowel disease, which further supports the crucial role of EZH2 for Treg function." (PMID 29619032, 2018). "Interestingly, methylation alteration was found in inflammatory disease model, particularly EZH2 catalyzes trimethylation of histone 3 lysine 27 (H3K27me3) is critical for ameliorate the intestinal immune regulation during inflammatory bowel disease (IBD)." (PMID 39086963, 2022). "However, there are also reports that intestinal mucosal epithelial EZH2 has a strong protective effect on experimentally induced inflammatory bowel disease." (PMID 34899918, 2021). "EZH2 was shown to have an impact on the preservation of the epithelial cell barrier in the context of inflammatory bowel disease (IBD)." (PMID 40723311, 2025). "EZH2 expression was decreased in inflammatory bowel disease (IBD), and downregulation of EZH2 increased the expression of many inflammatory factors." (PMID 35432300, 2022). "However, evidence is lacking to address the effect of EZH2 enzyme’s activity on intestinal immune responses during inflammatory bowel disease (IBD)." (PMID 31160593, 2019).